CD24 (CD24 molecule)
Diseases named in the same sentence as CD24 in open-access papers (continued):
Sharing a sentence is not in itself a finding about the gene and the disease.
cancer (continued). "TAMR and ADR cells showed a significant increase in CSC population, which was revealed by the sphere-forming ability and relative number of CSCs that were identified with antibodies specific to cancer stem cell surface markers, CD24 negative and CD44 positive (CD24-/CD44+)." (PMID 38664825, 2024). "Finally, IWP-2 treatment could also attenuate the expressions of markers of EMT (enhanced E-cadherin and reduced vimentin levels) and cancer stemness (reduced CD44 and Oct4a but increased CD24 levels) as seen in the castration-relapse VCaP-NURR1 tumors." (PMID 38531859, 2024). "We also emphasize the significance of CD24 in both cancer and non-neoplastic conditions." (PMID 38313430, 2023). "However, reports indicate that CD24 silencing does not downregulate Src in certain cancer cell lines, like SKBR-3, and actually upregulates Src in others, like MDA-MB-468." (PMID 38137380, 2023). "In this setting, CD24 might play a critical role in the anti‐phagocytic signal, since MCL and CLL represent a subset of B‐cell malignancies with a considerable hostile TME with M2‐like TAMs, able to jeopardize anti‐cancer immunity." (PMID 37654003, 2023). "Scientists were able to identify a minor fraction (0.2–0.8%) of carcinoma cells, co-expressing CD24, CD44 and epithelial-specific antigen (ESA) and featuring high tumorigenicity, self-renewal capabilities and the ability to produce phenotypically diverse cancer cells." (PMID 37108193, 2023). "Furthermore, we shed light on the ongoing clinical progress in targeting CD24 and identify the obstacles and possible remedies within the realm of cancer immunotherapy and non-neoplastic disorders." (PMID 38313430, 2023). "Cancer stem cells markers represented by CD133 expression were present in a broad range from 0.0% to 46.0% with a median value of 0.5%; CD44 from 20.0% to 100.0% (median value 91.0%); and cells with CD24 expression were present from 0.0% to 16.0% (median value 7.0%)." (PMID 37958844, 2023). "The CD24+/CD44+ cells with high COL11A1 expression may undergo EMT.COL11A1 is absent in normal pancreatic tissues, which may be a crucial factor for distinguishing between cancer initiation and development." (PMID 35327583, 2022). "We observed promoter hypermethylation for the CD24, CD133, and CD147 genes at 70%, 75%, and 70%, respectively, in OSCC cell lines compared to normal oral mucosa tissues (<53%), indicating that this methylation pattern is cancer-specific, which was confirmed by bisulfite sequencing analysis." (PMID 36498950, 2022). "In addition, the downregulation of SPN also induces an increase in the stemness properties of the cells, such as the expression of some cancer stem cell markers (NANOG, OCT4, SOX2, and KLF4) and enrichment in CD44+/CD24- cells, cancer-initiating cells in breast tumors with stem cell properties." (PMID 34066428, 2021). "However, most of them aim to target CD24 on cancer cells and were not studied as immune checkpoint inhibitors to reactivate phagocytosis by TAMs." (PMID 33919517, 2021). "The identification and enrichment of cancer stem cells have been described in various cancer models, and the methods most commonly involve the detection of specific cell-surface markers (e.g., CD133, CD44, CD24) and cytoplasmic proteins (e.g., aldehyde dehydrogenase, ALDH1)." (PMID 34287231, 2021). "CD24 (heat-stable antigen) is a cell surface glycosylphosphatidylinositol-anchored protein expressed widely on various cell types, including hematopoietic T- and B-cells and APCs, nonhematopoietic cells, and cancer cells." (PMID 33748077, 2021). "Several other molecules, including CD44, CD133, CD24, and CD166 are potential cancer stem cell markers that may contribute to CRC progression and metastasis; therefore, we assessed if their expression correlated with that of EPHB3 in the CSC samples and controls." (PMID 32294981, 2020).
cancer (continued). "An immunophenotypic analysis revealed that ZJU-0430 cells were positive for CD24, CD44, CD29 and CD133 expression, and partially positive for CD184, and CD326 expression, and negative for CD34, CD90, CD117, and CD338 expression, similar to the primary cancer cells." (PMID 31367188, 2019). "Moreover, tocilizumab repressed the MCT-1-induced CD44(+)/CD24(−) subpopulations (55.7%) to the control degree (32.5%), confirming that IL-6R immunotherapy inhibited MCT-1-promoted cancer stemness." (PMID 30885232, 2019). "However, despite the well-documented function of CD24 overexpression in tumorigenesis, the driving force of CD24 overexpression in cancer has not been systematically investigated." (PMID 31244889, 2019). "The clinical utility of CD24 as a biomarker for cancer detection has not been determined." (PMID 30327565, 2018). "However, its contribution to cancer stem cell (CSC)-like traits and the clinical utility of CD24 as a urinary biomarker for cancer detection have not been determined." (PMID 30327565, 2018). "In addition to EpCAM, Dt81Hepa1-6 cells express both CD24 and CD44 (data not shown), two markers of increased tumorigenicity that have also been associated with cancer stem cells." (PMID 28152020, 2017). "To investigate whether cancer stem cell markers were over-expressed in HCC specimens, we retrospectively evaluated the expression levels of five cancer stem cell markers (CD90, CD44, CD133, CD13 and CD24) using IHC in 61 matched human HCC specimens and adjacent liver specimens." (PMID 26735577, 2016). "In this study, we found that HCC patients with different CSC markers (CD133, CD90, CD13, CD24 or CD44) possessed distinct clinic-pathological features, suggesting that these cells with different cancer stem cell markers may be present in an identical HCC population." (PMID 26735577, 2016). "More specifically, CD24 could act from the cell membrane through BMI1 and/or Nanog to control the expression levels of MDR genes, CCND1 and DNA repair genes like L1CAM and NBS1 to combat cisplatin-induced toxicity and damage to the cancer cells." (PMID 27276062, 2016). "However, stemness concomitant with EMT could also be considered as the emergence or increase of cancer stem cells (CSCs), which have enhanced tumorigenicity, partial stemness as in self-renewal and differentiation, and CD44+/CD24-/low on cell surface." (PMID 27258544, 2016). "In addition to EpCAM, a number of other biomarkers, such as CD133, CD44, CD24 and CD13, have been reported as biomarkers of HCC cancer stem cells, and it would be highly interesting to characterize cultured 3D spheroids for these stem cell markers in future studies." (PMID 26880118, 2016). "We also concluded that the CD44/CD24 combination does not enrich for cancer stem cells." (PMID 26449187, 2015). "In addition to the work performed with ALDH/CD44, we have also performed extensive testing of three additional putative stem cell marker combinations (CD10/CD24, CD44/CD24, CD10/CD44) to determine if these markers could enrich for cancer stem cells in vivo." (PMID 26449187, 2015). "However, CD24 is not a suitable therapeutic target; instead we suggest here new potential targets accounting for early differentiated cancer cells tumorigenic capacity." (PMID 26040280, 2015). "Additionally, mouse mammary epithelial or carcinoma stem cells express increased levels of CD49f and moderately increased CD24 levels, when compared to cells lacking self-renewal and gland-reconstituting capacities." (PMID 26680585, 2015). "Whether or not CD24+/CD44+ cells represent a potential phenotype of cancer stem cells in HNSCC remains to be determined." (PMID 24612587, 2014). "Furthermore, IWP-2 significantly reduced the cancer stem cell population in tamoxifen resistant cells, as confirmed by reduced capacity for mammosphere formation and a reduction in the percentage of CD44+CD24−/low cells." (PMID 24178749, 2014).
cancer (continued). "However, including CD44 and CD24, no marker can be used universally to identify CSCs in various cancers." (PMID 22693526, 2012). "However, studies on cancer cell lines showed substantial variation in CD44 and CD24 expression." (PMID 22693526, 2012). "Thus, expression of other transporters, or different drug resistance mechanisms, such as aldehyde dehydrogenase, which was over-expressed in both CD44+/CD24- and CD133+ cell types, may be operational in Brca1 cancer stem cells." (PMID 18241344, 2008). "Thus, at sites of metastasis, cancer cell phenotype based on CD44 and CD24 expression does not change significantly compared with that of parental cancer cells." (PMID 17062128, 2006). "Thus, steps in the cascade of events required for the spread of cancer are dependent on distinct groups of genes, and the CD44+/CD24- phenotype may define the expression of the group of genes involved in invasion." (PMID 17062128, 2006). "Cell sorting based on CD44 and CD24 expression or ALDH (aldehyde dehydrogenase) activity revealed that most Sox2 high expresser cells were not CD44hi/CD24lo- or ALDH-positive cells suggesting that they were not CSCs (cancer stem cells), though CD44 played a role in Sox2 expression." (PMID 33228022, 2020). "If CD24 mRNA should be detectable not only in tissue but also in prostatic secretions or even urine, the RT-PCR presented here could serve as an important noninvasive supplement to other procedures (digital rectal examination and serum PSA) within the framework of cancer screening." (PMID 16539730, 2006). "Combining with CD24 to deliver the “do not eat me” signal, CD47, an immune checkpoint receptor that is frequently dysregulated in malignant tumors, inhibits macrophage-mediated phagocytosis." (PMID 39256364, 2024). "CSCs in OvCa expressing CD133 and CD24 are chemoresistant, and spheroids with the presence of these markers can serve as a model for therapeutic approaches in regulation of CSCs markers expression because targeting one marker alone may be not sufficient to achieve the expected anti-cancer effect." (PMID 37958844, 2023). "Not surprisingly, similarity among different cancer types was identified in only 6 out of 23 clusters, including E3 (IRS2, KRT6A), E5 (CD24, STMN1), E8 (GKN1, MUC5AC), E9 (PHGR1, TFF3), E10 (TFF3, TPO) and E13 (VTN and ITIH5)." (PMID 36333338, 2022). "The data on the expression of stem cell markers CD44, CD24, and ALDH1A1 in the breast tissue of cancer-free women is very limited and no previous studies have explored the agreement between pathologist and computational assessments of these markers." (PMID 36590957, 2022). "This is consistent with reports that CD44+/CD24+ are generally non-tumorigenic, whereas CD44+/CD24-/low cells show cancer stem cell properties." (PMID 36009407, 2022). "CD15s expression was compared between mesenchymal-like cancer stem cells (CSC, CD44+CD24−), epithelial cells without CD44 (CD44−CD24+ and CD44−CD24−), and CD44+CD24+ cells that exhibit mesenchymal and epithelial features." (PMID 34206154, 2021). "CD15s expression was compared among mesenchymal-like cancer stem cells (CSC, CD44+CD24−), epithelial cells without CD44 (CD44−CD24+ and CD44−CD24−), and CD44+CD24+ cells that exhibit mesenchymal and epithelial features." (PMID 34206154, 2021). "We further compared the mRNA level of cancer stemness markers in AZD4547-treated (2 μM) vs. non-treated control L3.6 cells and found that CD24, CD44, and CD133, were dramatically down-regulated upon AZD4547 treatment." (PMID 32457900, 2020). "The heat-stable antigen CD24, a glycosylphosphatidylinositol-anchored membrane glycoprotein, has been extensively used as a negative or positive marker of CSC in various cancer types." (PMID 28320418, 2017).
cancer (continued). "The cell population, characterized by the marker profile CD24+CD90+CD45−, showed a high tumorigenicity compared to non-CD24+CD90+CD45− cancer cells in colony formation assays, as well as upon orthotopic transplantation into the mammary fat pad of mice." (PMID 27542270, 2016). "In double-staining IHC, ALDH1A1 was not co-expressed with BMI1, EpCAM, CD13, CD24, CD90 and CD133, which reported as cancer stem cell markers in HCC." (PMID 26160842, 2015). "Under these conditions, I3C treatment of 10AT-Her2 cells did not alter the expression of the cancer stem/progenitor cell-like marker proteins nucleostemin, CD44, CD24 and ALDH-1." (PMID 25209720, 2014). "Therefore, despite its lack of a cytoplasmic signaling domain, CD24 has the capacity to recruit crucial signaling molecules, such as EGFR, ERK, and AKT, and promote tumorigenicity in both cancer cells and CSCs." (PMID 38881902, 2024). "Similarly, lipid rafts (LRs) are significantly enriched in cancer stem cells (CSCs) compared to non-stem cancer cells, and key CSC markers, such as CD24, CD44, and CD133, are located within these lipid rafts, underscoring their pivotal role in CSCs." (PMID 38396837, 2024). "The authors injected CD44+CD24+/ESA+ cancer cells in immunocompromised mice and observed a 100-fold increase in tumorigenic potential when compared to those mice injected with nontumorigenic cancer cells." (PMID 36776295, 2023). "However, unlike PD-L1, CD24 and CD47 protected cancer cells from attack by directly interacting with the Siglec-10 signaling pathway in macrophages." (PMID 37875918, 2023). "Thus, CD24 antibody treatment potentiated phagocytosis with greater effect in vitro than CD47 mAb treatment in MCL and carcinoma, but not in DLBCL." (PMID 35625912, 2022). "Cancer stem cells of BC strongly express CD44, together with no or very low levels of CD24." (PMID 30691317, 2019). "As numbers of studies found that cell stemness/differentiation may contribute to chemoresistance in cancers, negative correlations between PKM2 expression and stemness markers, including Sox2, CD24, and Prom1/CD133 mRNA levels, were detected in subjects from the TCGA-HNSC dataset." (PMID 38068962, 2023). "Finally, ESA+/CD24−/low/CD44+ cancer stem cells from RB-negative TNBC lines were consistently more sensitive to gamma-irradiation than RB-positive lines, whereas the effect of chemotherapy on the cancer stem cell fraction varied irrespective of RB1 expression." (PMID 24265703, 2013). "Based on these experiments, either chemotherapy drug resistant or irradiation resistant cancer stem-like cells were identified in cell culture and no further recurrence was seen in treated mice carrying tumors derived from both ALDEFLUOR-positive cell population and CD24+ cell population." (PMID 22901246, 2012). "Furthermore, the decrease in cancer stem cells surface markers phenotype (CD90, CD44, CD133, CD13 and CD24) observed in combined DATP and XAV939 was no more than that observed by either individual treatment, suggesting that Notch and Wnt/β-Catenin may have cross-talk between each other." (PMID 26735577, 2016).
infection (45 papers, 2008 to 2025). The state of being infected such as from the introduction of a foreign agent such as serum, vaccine, antigenic substance or organism. "CD24 has been found to be upregulated in response to viral and bacterial infections, and CD24-deficient mice have been shown to be more susceptible to infection." (PMID 38313430, 2023). "At 6 weeks post infection, gradual loss (CD24) and gain (CD127 and Qa2) of surface antigen expression by CD8+ RTEs revealed a prototypic status of post-thymic maturation in FV-infected mice." (PMID 24651250, 2014). "We also showed that infection of neonatal brain leads to abnormal development as indicated by loss of CD24 (hi) cells that incorporated BrdU." (PMID 21249143, 2011). "We also showed that infection of neonates leads to subsequent abnormal brain development as indicated by loss of CD24(hi) cells that incorporated BrdU." (PMID 21249143, 2011). "Another Egyptian study detected that CD24 polymorphism 170 CT/TT may affect the incidence of infection with CHC, as well as HCC." (PMID 36900128, 2023). "Higher levels of B regulatory cells (B regs, CD24 high/CD38 high) were detected in the early phase of the MPXV infection (T0 = 3.0% vs. T2 = 1.1%, p = 0.017)." (PMID 40005722, 2025). "As expected, EC subsets (AT1, AT2, and CD24 + EC) had the highest number of viral copies per μg of RNA, suggestive of active infection." (PMID 38086794, 2023). "Ly6A/E expression was not impacted by anti-IFNγ treatment, but BST2 was significantly reduced, albeit modestly, in AT2 and CD24 + EC, the two major cell types that are targeted for infection by SARS-CoV-2." (PMID 38086794, 2023). "CD24 interacted with Siglec‐10 on innate immune cells to dampen damaging inflammatory responses to infection." (PMID 37519221, 2023). "The permissivity of CD24-low cells to infection with ZIKV, PIV5-P/V, and VSV-EGFP differed substantially." (PMID 36016357, 2022). "Why does CD24 expression have differing effects on permissivity to infections with these three RNA viruses?" (PMID 36016357, 2022). "Most strikingly, our data show that ectopic expression of CD24 increases the permissivity of CD24-high cells to infection with three different RNA viruses—ZIKV, VSV, and PIV5-P/V." (PMID 36016357, 2022). "Infection of CD24-low cells showed a minimal percentage of Env+ cells (~1–5%) across the time course, compared to infection of CD24-high cells, which led to ~50% Env+ cells by 3 dpi." (PMID 36016357, 2022). "The presence of CD24 made it convenient to track active infections by flow cytometry using FITC labelled rat-anti-murine CD24 antibodies." (PMID 34233649, 2021). "Although the difference of the infection proportion gradually narrowed in 36 h post infection, CD24+SSClow cells still contained more intracellular TGEV." (PMID 31959773, 2020). "Removing CD13+ cells didn’t affect the number of CD24+SSChigh and CD24+SSClow cells in CD13+-removed IPEC-J2 cells, even upon TGEV infection and rescued Lgr5 ISCs loss, which was induced by TGEV." (PMID 31959773, 2020). "To validate the RNA-sequencing data, we sorted murine ciliated cells based on CD24 and tdTomato as a marker of infection and performed quantitative reverse transcription PCR (qRT-PCR) for some of the genes most dysregulated in survivor cells." (PMID 30770807, 2019). "We, therefore, infected tdTomato transgenic mice with Mal/04-Cre and collected CD24 + ciliated cells at 14 days post-infection." (PMID 30770807, 2019). "By Day 3 post-infection, viral titers remained ~10 to 100 fold greater in the CD24-expressing cells compared to controls (2 x 104 versus 2 x 105 or 3 x 106, respectively)." (PMID 30044847, 2018). "Complementation of CD24 expression in these cells led to the production of detectable levels of NS1 expression after infection with Zika, as well as dramatic increases in viral titers and CPE." (PMID 30044847, 2018).